TERT (telomerase reverse transcriptase)
Diseases named in the same sentence as TERT in open-access papers (continued):
Sharing a sentence is not in itself a finding about the gene and the disease.
Hyperkeratosis (1 paper, 2016). Hyperkeratosis is a histopathological term defining a thickened stratum corneum and may be present in many different skin conditions, with many possible overlaps. "In people exposed to arsenic via drinking water (1–1000 μg/L) in Inner Mongolia, TERT expression was positively associated with arsenic concentrations in water and in fingernails, and with the severity of arsenic related hyperkeratosis." (PMID 27597942, 2016).
IgA nephropathy (1 paper, 2024). "Moreover, there is a published literature report on epigenome-wide association study (EGWAS) for IgA nephropathy, and they found that three methylation CpGs corresponding to TERT were significantly associated with IgA nephropathy." (PMID 38197421, 2024).
inflammatory skin disease (1 paper, 2017). Inflammatory skin disorders covers a broad category that includes many conditions ranging in severity, from mild itching to grave medical health complications These disorders are common in people of all ages and races. "To illustrate the potential of N/TERT keratinocytes for studies on epidermal biology, inflammatory skin disease pathogenesis and therapeutics, we compared the mRNA and protein expression of two N/TERT keratinocyte cell lines to that of human primary epidermal keratinocytes in monolayer cultures." (PMID 28928444, 2017).
influenza (1 paper, 2015). An acute viral infection of the respiratory tract, occurring in isolated cases, in epidemics, or in pandemics; it is caused by serologically different strains of viruses (influenzaviruses) designated A, B, and C, has a 3-day incubation period, and usually lasts for 3 to 10 days. "We assessed the correlations between influenza vaccine-specific humoral immunity measures and other overall humoral immune response variables measured over time, and age/immunosenescent markers (TREC, TERT, CD28 expression on CD4+ and CD8+ T cells)." (PMID 25816015, 2015).
keloid (1 paper, 2021). An irregularly shaped, elevated mark on the skin caused by deposits of excessive amounts of collagen during wound healing. "Furthermore, nine core miRNAs (hsa-mir-124, hsa-let-7, hsa-mir-155, hsa-mir-26a, hsa-mir-941, hsa-mir-10b, hsa-mir-20, hsa-mir-31 and hsa-mir-372), and two core TFs (SP1 and TERT) were identified to play important roles in keloid formation." (PMID 34600545, 2021).
lentivirus infection (1 paper, 2020). Virus diseases caused by the Lentivirus genus. "To test whether NCOA3 bound to the TERT promoter to activate TERT transcription, we established HCC cell lines with stable knockdown or overexpression of NCOA3 by lentivirus infection." (PMID 33239622, 2020).
Lymphadenopathy (1 paper, 2022). Enlargement (swelling) of a lymph node. "As for sex differences, men had more commonly presented lymphadenopathy (p = 0.014), minimally invasive carcinoma (p = 0.002), positive TERT mutation (p < 0.01) and higher TNM (8th edition) staging of TC (p < 0.01) in comparison to women." (PMID 35625691, 2022).
male infertility (1 paper, 2021). The inability of the male to effect fertilization of an ovum after a specified period of unprotected intercourse. "The TERT rs2736100 was inversely associated with male infertility risk, whereas TEP1 rs1713449 was positively associated with risk of male infertility, constituting that STLs could indeed pose as a risk factor for male infertility." (PMID 34842724, 2021).
malignant meningioma (1 paper, 2020). "Emerging genotypical prognostic factors, such as the TERT promoter mutation, have shown both spatial and temporal heterogeneity in high grade and malignant meningioma." (PMID 33198268, 2020).
malignant peritoneal mesothelioma (1 paper, 2025). An aggressive malignant mesothelioma that arises from the peritoneum. "The TERT mRNA expression quantification, represented as red dots, in malignant peritoneal mesothelioma showed a different expression panel among the different histotypes." (PMID 39858033, 2025).
malignant pleural mesothelioma (1 paper, 2018). A malignant neoplasm that arises from mesothelial cells in the pleura and shows a diffuse growth pattern. "Hotspot mutations in the Telomerase reverse transcriptase (TERT) promoter gene, occurring in 15% of patients with malignant pleural mesothelioma (MPM), was reported to up-regulate TERT in MPM." (PMID 29949944, 2018).
Malignant Salivary Gland Tumors (1 paper, 2023). "Therefore, the present study was performed to evaluate TERT Promoter mutations in benign and malignant salivary gland tumors." (PMID 37383158, 2023).
MALT lymphoma (1 paper, 2019). An indolent, extranodal type of non-Hodgkin lymphoma composed of small B-lymphocytes (centrocyte-like cells). "Human TERT (hTERT) gene expression was measured by RT-qPCR in the gastric epithelial cell line AGS, infected for 24°h with H. pylori strain B38, a clinical isolate from a MALT lymphoma patient." (PMID 32082377, 2019).
melanocytic nevus (1 paper, 2021). A neoplasm composed of melanocytes that usually appears as a dark spot on the skin. "We did find an association between the presence of a TERT promoter mutation and the origin of the lesion (p-value = 0.005), with most cases (54%) developing either de novo or from a melanocytic nevus." (PMID 34071371, 2021).
memory impairment (1 paper, 2024). "Overexpression of TERT by AD‐mTERT‐GFP reversed both chronic stresses‐ and ADX‐induced deficiency of TERT and the proliferation and development of NSCs, chronic stresses‐associated depressive symptoms, and ADX‐associated learning and memory impairment." (PMID 38421107, 2024).
monocytic leukemia (1 paper, 2015). "Using human monocytic leukemia cell line THP-1, we conducted a broad screen targeting 5'-mono-phosphorylated, 5'-hydroxylated and 5'-capped short RNAs after the transfection of a gene-specific siRNA for TERT or a control siRNA." (PMID 25569094, 2015).
mucinous carcinomas (1 paper, 2018). "TERT methylation was observed in 71% of serous and 50% of mucinous carcinomas." (PMID 29882921, 2018).
multiple sclerosis (1 paper, 2024). A progressive autoimmune disorder affecting the central nervous system resulting in demyelination. "The genetic features of multiple sclerosis include a high frequency of hotspot mutations (C228T or C250T) in the promoter region of TERT, which encodes the TERT protein, and FUS-DDIT3 or EWSR1-DDIT3 gene fusion." (PMID 39239547, 2024).
Myelodysplasia (1 paper, 2023). Clonal hematopoietic stem cell disorders characterized by dysplasia (ineffective production) in one or more hematopoietic cell lineages, leading to anemia and cytopenia. "Interestingly, our results reported that one patient, who was a compound heterozygote for two TERT gene variants (c.835G>A/c.2031C>T), suffered relapse and development of myelodysplasia following therapy." (PMID 38017244, 2023).
myeloid leukaemia (1 paper, 2017). "We initially verified TERT expression and activity in both PBMCs isolated from HLA-A2+ AML patients or HD and THP1 human myeloid leukaemia-immortalized cells." (PMID 29152058, 2017).
neuronal tumor (1 paper, 2023). Neuronal brain tumors are an uncommon group of central nervous system tumors that arise from cells with neuronal differentiation. "In pediatric-type diffuse gliomas and glioneuronal and neuronal tumors, alterations in EGFR and TERT were correlated with a poor prognosis, respectively." (PMID 36998447, 2023).
oral cavity cancer (1 paper, 2023). A primary or metastatic malignant neoplasm involving the oral cavity. "The anatomic distribution of cases is strongly associated with TERT promoter mutations, and the highest frequency is in oral cavity cancers." (PMID 36979671, 2023).
oropharyngeal cancer (1 paper, 2019). Carcinoma, predominantly squamous cell, arising from the epithelial cells of the oropharynx. "Furthermore, patients with HPV-driven oropharyngeal cancer had higher levels of TERT in SM." (PMID 31772219, 2019). "Among oropharyngeal cancers, patients with HPV-driven oropharyngeal cancer reported higher TERT levels in SM (P < 0.001)." (PMID 31772219, 2019).
ovarian endometrioid carcinoma (1 paper, 2025). "Thus, constitutive expression of CDK4R24C, cyclin D1 and TERT genes may be an option for establishing cell lines from low-grade cancers, including ovarian endometrioid carcinoma." (PMID 39878900, 2025). "In the present study, we established the human ovarian endometrioid carcinoma cell line JFE-21 by constitutive expression of exogenous CDK4R24C, cyclin D1 and TERT genes." (PMID 39878900, 2025).
panic disorder (1 paper, 2024). An anxiety disorder characterized by multiple unexpected panic attacks with persistent concern of recurring attacks. "Meanwhile, TERT methylation impacts social functioning in patients with panic disorder by regulating the function of the left postcentral gyrus." (PMID 38315329, 2024).
papilloma (1 paper, 2021). A benign epithelial neoplasm that projects above the surrounding epithelial surface and consists of villous or arborescent outgrowths of fibrovascular stroma. "K5-TERT mice, which overexpress TERT in their skin, develop more papillomas when exposed to chemical carcinogen TPA as compared to wild-type controls." (PMID 33599797, 2021).
peripheral arterial disease (1 paper, 2012). A disorder of the arteries supplying the upper and lower extremity and the visceral organs. "Association between variants in the TERT gene and risk of peripheral arterial disease." (PMID 23082138, 2012).
placental insufficiency (1 paper, 2013). Failure of the placenta to deliver an adequate supply of nutrients and oxygen to the fetus. "TERT expression would be a limiting factor on telomerase activity at placental level, and as a result, its lower expression could account for the reduction of telomere length that we report during pregnancies with an IUGR secondary to placental insufficiency." (PMID 23326560, 2013).
posterior fossa ependymoma (1 paper, 2016). A high grade ependymoma that is located within the posterior fossa. "Only recently did Castelo-Branco and co-workers report that the TERT promoter methylation increased with cancer progression and could serve as a useful prognostic factor in posterior fossa ependymomas." (PMID 26870890, 2016).
premature aging (1 paper, 2019). "Moreover, EO totally avoided the possible premature aging syndrome caused by mercury exposure, preserving the TERT expression." (PMID 31717801, 2019).
Respiratory insufficiency (1 paper, 2010). "For most of the TERT mutation carriers, the cause of death was related to respiratory insufficiency." (PMID 20502709, 2010).
Seckel syndrome (1 paper, 2014). A rare autosomal recessive inherited syndrome caused by mutations in the ATR gene, RBBP8 gene, CENPJ gene, CEP152 gene, CEP63 gene, NIN gene, DNA2 gene, or TRAIP gene. "As reference controls, two h-TERT immortalized skin fibroblast lines were included in the analysis: (i) 1BR, obtained from a normal ATR-proficient individual, and (ii) F02-98, derived from a patient afflicted with Seckel syndrome, characterized by hypomorphic ATR deficiency." (PMID 24416382, 2014).
silicosis (1 paper, 2025). Silicosis is a respiratory disease caused by breathing in (inhaling) silica dust. "Among the patients with silicosis, 8.3% had TERT variants and no TERC variants were detected." (PMID 39813504, 2025).
skin atrophy (1 paper, 2019). The degeneration and thinning of the epidermis and dermis. "Patients with mutations in the telomerase component (eg, Dyskerin, TERT, TERC) are frequently accompanied by symptoms of abnormal epidermis, such as hyperpigmentation, premature skin degradation, hair follicle shedding, skin atrophy, and dry skin." (PMID 31518356, 2019). "Moreover, patients with the mutation of telomerase components (e.g. Dyskerin, TERT, TERC) exhibit telomere shortening and skin atrophy." (PMID 31518356, 2019).
Splenomegaly (1 paper, 2023). Abnormal increased size of the spleen. "Additionally, the TERT (rs2736098*A/A) genotype revealed a noticeable association with positive smoking and splenomegaly (p-value < 0.05)." (PMID 37884663, 2023).
T-cell lymphoma (1 paper, 2010). "In this study, we aimed to use the Marek's disease virus (MDV) T-cell lymphoma model to evaluate TERT regulation by splicing during lymphomagenesis in vivo, from the start point to tumor establishment." (PMID 20964812, 2010).
thrombosis (1 paper, 2023). "Thrombotic risk did not depend on JAK2 rs12343867, TERT rs2736100, OBFC1 rs9420907 SNV, however, we found a novel strong tendency towards statistical significance between the CC genotype miR-146a rs2431697 and thrombosis." (PMID 36242602, 2023).
thymoma (1 paper, 2019). A neoplasm arising from the epithelial cells of the thymus. "The best performance of the MIPRIP 2.0 multi-mode analysis was observed for thymoma and testicular germ cell cancer, which showed also the highest TERT expression." (PMID 31888467, 2019). "The highest correlation was found for testicular germ cell cancer (TGCT) (r = 0.75) and thymoma (THYM) (r = 0.7), which also showed the highest TERT expression over all cancer types." (PMID 31888467, 2019).
tubular adenoma (1 paper, 2020). A usually polypoid neoplasm arising from the glandular epithelium. "In conclusion, we confirmed that TERT expression has a possible role in the tubular adenoma-carcinoma pathway." (PMID 32932803, 2020).
tumors of the vulva (1 paper, 2015). "Despite the low frequency of the TERT mutation in tumors of the vulva, 25%, it may be important in a subset of SCC." (PMID 25823555, 2015). "Our results showed that HMGA2 and TERT may be of importance in the genesis and/or the progression of tumors of the vulva." (PMID 25823555, 2015). "We report a detailed study of 25 vulva tumors [22 SCC, 2 MM, 1 atypical squamous cell hyperplasia (AH)] analyzed for expression of the high-mobility group AT-hook family member genes HMGA2 and HMGA1, for mutations in the IDH1, IDH2 and TERT genes, and for methylation of the MGMT promoter." (PMID 25823555, 2015).
urothelial neoplasm (1 paper, 2018). A neoplasm involving a urothelium. "High rates of activating mutations in the upstream promoter of the TERT gene are found in the majority of urothelial neoplasms of both upper and lower tracts." (PMID 29557778, 2018). "TERT promoter mutations have thus been established as a common genetic alteration in urothelial neoplasms." (PMID 29557778, 2018).
urothelial papilloma (1 paper, 2020). A rare benign condition, characterized by a papillary growth in the urinary tract with a central fibrovascular core. "Moreover, in a recently reported study of inverted and exophytic urothelial papillomas, no TERT-promoter mutations were identified in 11 cases." (PMID 32213857, 2020).
Uterine leiomyoma (1 paper, 2020). The presence of a leiomyoma of the uterus. "Although the effect of uterine leiomyoma risk allele on telomere length is inverted between TERT and TERC loci, the relationship between telomere length and neoplastic disease risk is contradictory." (PMID 31988393, 2020).
Werner syndrome (1 paper, 2009). "Significant age-related methylation alterations in telomere maintenance gene-loci TERT, ERCC1, RAD50, and the Werner syndrome gene-locus (WRN) were also observed." (PMID 19680444, 2009).
ZIKV infection (1 paper, 2017). "Further examination of the roles of metabolic control genes such as TERT, ALDH7A1, CREB5, EAPP, and NDUFA11 as they relate to ZIKV infection may provide further insights into ZIKV pathogenesis." (PMID 28442752, 2017).
tumor (1,388 papers, 2002 to 2026). "For all the tumor specimens tested, in addition to TERT and HRAS alterations, several other oncogenic variants have also been found." (PMID 41489678, 2026). "The difference in TL between tumor and germline was significantly larger in tumors harboring TERT-promoter mutations (tumor–germline TL difference: -1700 for mutated and -945 for wild-type, t test P = 0.0068)." (PMID 41563788, 2026). "Genetic alterations including BRAF V600E and TERT promoter mutations are associated with dedifferentiated tumor phenotypes and poor radioiodine response." (PMID 42042023, 2026). "Nevertheless, several recent discoveries, including the identification of recurrent somatic mutations in the TERT promoter in various cancer types, indicate that mutations in noncoding regions are also crucial in tumour development." (PMID 41344988, 2026). "Then, we have evaluated the concordance of TERT promoter mutations in DNA extracted from matched oral rinse and tumor tissue samples of HNSCC patients." (PMID 41487579, 2025). "For example, mutations in the TERT promoter increase telomerase activity, providing tumor cells a growth benefit and consistently linking to reduced overall survival." (PMID 40058218, 2025). "This case underscores the diagnostic, molecular, and prognostic complexities of spinal CM and highlights the critical role of TERT promoter mutation in tumor behavior and classification." (PMID 41013491, 2025). "PI3K pathway mutations, observed in both DTC and ATC, are less frequent than BRAF and TERT mutations but are consistently linked to survival outcomes, underscoring their role in tumor progression." (PMID 40149275, 2025). "Although RAS mutations alone are insufficient to drive full malignant transformation, the presence of co-occurring mutations, particularly TERT promoter mutations, has been linked to more aggressive tumor phenotypes and increased mortality in RAS-mutant DTCs." (PMID 40927522, 2025). "TERT-mutation cfDNA blood plasma levels rose up to 5.6-fold in a cohort of four patients, indicating that focused ultrasound increased tumor-derived cfDNA." (PMID 40285800, 2025). "Somatic mutations in the TERT promoter region were found to be the most common, occurring in 44% of tumor samples." (PMID 40995307, 2025). "Several studies reveal a strong association between increased TERT levels and the enhanced proliferation and viability of tumor B cells." (PMID 40227701, 2025). "In the majority of patients with UCB, TERT promoter mutations in urine rapidly disappear following tumor resection." (PMID 39871386, 2025). "TERT promoter mutations are the most common clonally activating mutations, maintaining telomere length through TERT overexpression and achieving immortalization of tumor cells." (PMID 41201287, 2025). "Tumors with TERT promotor mutations are more likely to have a larger tumor, recurrence, vascular invasion, and local node metastasis." (PMID 40307280, 2025). "While normally silent in most adult tissues, mutations in the TERT promoter can lead to aberrant gene activation, promoting unchecked cellular proliferation and contributing to tumor progression and aggressiveness." (PMID 40940948, 2025). "For instance, BRAFV600E activates the MAPK pathway, while TERT promoter mutations increase telomerase activity, accelerating tumor growth and invasion." (PMID 40895628, 2025).